SNORD114-3 (small nucleolar RNA, C/D box 114-3)
Synonyms: 14q(II-3)
Gene: Small nucleolar RNA gene on chromosome 14 (100,953,349 to 100,953,423, forward strand). Ensembl gene ENSG00000201839.
Gene Ontology:
Biological process: RNA processing
Cellular component: nucleolus
Homologues: Orthologues: chimpanzee SNORD114-3 (100% identical), macaque SNORD114-3 (95% identical), mouse Gm23736 (73% identical), rat Snord113l1 (71% identical), mouse Gm22981 (68% identical), rat LOC120093391 (65% identical), mouse AF357341 (60% identical), mouse AF357428 (59% identical), mouse Gm25856 (57% identical). Paralogues in human: SNORD114-17 (89% identical), SNORD114-12 (85% identical), SNORD114-14 (85% identical), SNORD114-21 (85% identical), SNORD114-23 (85% identical), SNORD114-13 (84% identical), SNORD114-1 (83% identical), SNORD114-11 (83% identical), SNORD114-15 (83% identical), SNORD114-26 (83% identical), SNORD114-18 (81% identical), SNORD114-28 (81% identical), and 26 more.
Diseases named in the same sentence as SNORD114-3 in open-access papers:
SNORD114-3 is named in the same sentence as 2 diseases in open-access papers, as found by Europe PMC text mining. Sharing a sentence is not in itself a finding about the gene and the disease.
SNORD114-3 shares sentences with these, for which no sentence is quoted: acute promyelocytic leukemia (1 paper); cancer (1).